KRT8 (keratin 8)
Diseases named in the same sentence as KRT8 in open-access papers (continued):
Sharing a sentence is not in itself a finding about the gene and the disease.
cancer (continued). "GPR12 has been reported to be relevant to cancer metastasis via modulating the viscoelasticity of metastatic cancer cells by influencing phosphorylation and reorganization of keratin 8 filaments." (PMID 35903681, 2022). "Krt8-expressing cells were observed in most cancer clusters but were few in the stem-like cell cluster." (PMID 34785704, 2021). "The expression of Krt8 increased with pseudotime in the cancer organoids but was high in both stem-like and differentiated cells in the control organoids." (PMID 34785704, 2021). "To characterize the obtained cultures, we performed immunofluorescent staining for Cytokeratin 8 (CK8) that is abundantly present in epithelial cells and overexpressed on several types of cancers and in vitro cultured epithelial cells." (PMID 33922995, 2021). "Krt8 was widely expressed in cancer organoids but detected only in some suprabasal cells in the control organoids." (PMID 34785704, 2021). "A number of gene nodes linked to drug resistance in other cancer types (including CAT, TRIM59, ANXA2, ADM, AJUBA, HSPA1A/1B, LAMC2, TRIM14, KRT8, KRT18, KRT9, CLDN1, and SMARCA2) were also down-regulated in PARPis-sensitive AsPCs." (PMID 33213473, 2020). "Cytokeratin 8 (CK8) is a biomarker of cancer cells, and affects drug resistance and modulation of apoptotic resistance in cancers." (PMID 32513981, 2020). "We also detected enrichment for transcripts encoding fibroblast-specific protein 1 (FSP1/S100a4), keratins Krt7, Krt8, Krt14 and Krt18 and claudins Cldn3, Cldn4 and Cldn7 in this cluster which were also enriched in epithelial/cancer cells." (PMID 32455670, 2020). "For bone staining, we used keratin 8 + 18, a marker for cancer cells, and alkaline phosphatase (ALP), a marker for bone marrow mesenchymal stem cells." (PMID 32218208, 2020). "KRT8 is a type II basic intermediate filament (IF) protein, associated with EMT, which is essential for the occurrence and metastasis of various cancers." (PMID 33490259, 2020). "Keratin 8 (KRT8), a type II basic intermediate filament (IF) protein, is essential for the development and metastasis of various cancers." (PMID 30634629, 2019). "In the GSE6400 dataset, we found that KRT8 was significantly up-regulated in the A549 cell line treated with 1.25 μM and 2.5 μM of the anti-cancer agent sapphyrin PCI-2050 (p = 0.0006 and p = 0.0005, respectively)." (PMID 30634629, 2019). "PIWIL2 promoted cancer cell proliferation via increasing c-Myc expression by facilitating NME2 binding to the G4-motif, facilitated cancer cell migration via TBCB and resisted Fas-induced cancer cell apoptosis by inhibiting keratin 8 degradation." (PMID 29555935, 2018). "Consistent with its known role as a cancer biomarker, KRT8 expression was elevated in a majority of malignant tissue samples (n = 13; mean nuance score 331.3 ± 266 standard deviation, SD) versus non-malignant tissue (n = 4; 83.8 ± 58 SD, p = 0.017)." (PMID 29443941, 2018). "In Pten;Tgfbr2 tumors, the invasive cancer was highly proliferative and was largely Krt5-high and Krt8-low, whereas fewer cells stained positive for Ki67 in intact HGPIN ducts that were luminal." (PMID 29782499, 2018). "In this context, it is interesting to note that the widespread appearance of dual positive cells in the Krt8-CreERT2 model roughly coincides with the onset of extensive locally invasive cancer." (PMID 29782499, 2018). "Carcinomas arising from diverse tissues exhibit KRT8 mRNA and protein overexpression when compared to normal tissue levels." (PMID 29443941, 2018). "Though existing studies have identified that KRT8 expression is clinically significant in various cancers, the function and precise mechanisms of KRT8 in ccRCC are require further research." (PMID 29100303, 2017). "Keratin 8 (KRT8) plays an essential role in the development and metastasis of multiple human cancers." (PMID 29100303, 2017).
cancer (continued). "For example, the KAT6A promoter is more open specifically in MFD-1 cells (top) although at other loci, exemplified by the KRT8 gene, the chromatin associated with the TSS is more open in both MFD-1 and OE33 cancer cell lines compared to HET1A cells (bottom)." (PMID 27600491, 2016). "All carcinomas expressed varying levels of luminal epithelial markers, including Keratin-8 and E-Cadherin." (PMID 23173005, 2012). "In addition, NAT10 stabilizes KRT8 mRNA via ac4C acetylation, which drives cancer cell proliferation and metastasis." (PMID 41203621, 2025). "The highest expression of genes encoding Col1a1-2, Col3a1, Col4a1, Col4a2, Col5a1, Col5a2, Col6a1, Col8a1, Col9a3, Col10a1, Col12a1, Col14a1, Col15a1, Col16a1, Col18a1, and Col28a1 were detected in untreated tumors, whose landscapes were dominated by Krt8+ cancer cells." (PMID 39372930, 2024). "The epithelial and cancer cells showed higher KRT8, KRT18, KRT19 and ANXA4 expression." (PMID 39149248, 2024). "Overexpression of GPR12 induced keratin 8 phosphorylation and reorganization, which might contribute to cancer cell metastasis." (PMID 37789353, 2023). "Therefore, it is unsurprising that both keratin 18 and keratin 8 are often upregulated in most human cancer types." (PMID 35406424, 2022). "Recent evidence suggests that KRT8 overexpression on the cell surface might enhance cell adhesion to the extracellular matrix—raising questions about involvement of KRT8 in cancer-cell-signaling pathways." (PMID 34991727, 2022). "Moreover, earlier studies also showed that an increase in the protein abundance of both keratin 18 and keratin 8 in cancer cells enhances the migratory and invasive capacities of cancer cells and alters their interactions with extracellular environments." (PMID 35406424, 2022). "This is consistent with previous observations that, both KRT8 and KRT18 are over-expressed/aberrantly expressed in certain human cancers and such expression is associated with cancer progression/poor-prognosis." (PMID 34490045, 2021). "This suggests that, although KRT8 is a direct target gene, it is not involved in the cancer risk associated with the risk enhancer." (PMID 31328168, 2019). "Elevated keratin-8 (KRT8) protein expression is an established diagnostic cancer biomarker in several epithelial cancers (but not ATC)." (PMID 29443941, 2018). "However, in the Pten;Tgfbr2 tumors, a large proportion of the invasive cancer consisted of cells that were strongly positive for Krt5, with Krt8 cells intermixed." (PMID 29782499, 2018). "To test whether platelets infiltrate into solid tumors, we have examined platelet deposition in several types of human cancer specimens using immunofluorescent staining of βIIb for platelets, cytokeratin 8 (CK8) for tumor cells and DAPI for nuclear DNA." (PMID 25762641, 2015). "Indeed, overexpression of PLG-R including actin (ACT), enolase-1 (ENO-1), cytokeratin 8 (CK8) and annexin 2 (ANX2) has been associated with poor prognosis and resistance to chemotherapy of cancer patients." (PMID 25407528, 2014). "The data on the role of keratin 8 in cancer are inconsistent." (PMID 25503972, 2014). "KRT8 is aberrantly expressed in several cancers and may serve as a biomarker." (PMID 35664775, 2022). "The epithelial OC origin of the PDC2 and PDC3 samples was confirmed by the expression of OC-specific markers PAX8 and CD24, epithelial makers MKI67, EPCAM, KRT8 and KRT18 and cancer stem cell markers such as CD44 and ROR1." (PMID 39482470, 2025). "We detected cancer cells using markers typical of LUAD and alveolar epithelium (EPCAM, CDH1, KRT19, KRT18, KRT8)." (PMID 37745301, 2023). "Several KRT genes, including the phylogenetically older KRT8, KRT18, KRT19, KRT23, KRT79, KRT80 and KRT222, were found to be differentially expressed in diverse types of cancers." (PMID 36949761, 2023).
cancer (continued). "Several members of the KRT gene family, including the evolutionarily older KRT8, KRT18, KRT19, KRT23, KRT79, KRT80 and KRT222, were shown to be differentially regulated in diverse cancer types." (PMID 36949761, 2023). "In summary, our study indicates that the high expression of KRT8 regulates cell migration, invasion, and EMT by NF-κB signaling, contributing to cancer progression and poor survival in LUAD." (PMID 35664775, 2022). "ELF3, which is predicted to drive the expression of highly expressed ID genes ANXA3, TGFB2, and duct marker KRT8, has been shown to drive ligand-independent transactivation of CTNNB1 in cancer models." (PMID 36540608, 2022). "This technique identified cell clusters that, through marker genes, included cancer cells—markers EpCAM, KRT8, KRT18, and KRT23, fibroblasts—marker COL1A1 (cancer cells, 4389 cells; fibroblasts, 2549 cells)." (PMID 34026600, 2021). "Recently, single‐cell analysis of the transcriptome and epigenome also showed that KRT8, KRT18, CLDN4, KRT19, KRT20, etc. are highly expressed in CRCs,[12a] consistent with our results that these genes were highly expressed in cancer EPCs." (PMID 33898197, 2021). "Both KRT8 and KRT19 have been well demonstrated to function as two oncogenes in development of human cancers." (PMID 32519739, 2020). "Subpopulation B consisted of 121 cells (29.1%) and showed overexpression of 13 genes, including seven cancer genes (HSPB1, ANXA1, SLPI, KRT8, KRT19, KLK7, and ABL2) and several Keratin genes (KRT8, KRT7, KRT19, and KRT6B)." (PMID 28794488, 2017). "In line with the present results, we have previously reported overexpression of KRT8/18 and PHB1 as biomarkers of mouse liver preneoplastic lesions and tumors, showing the highest expression in carcinomas." (PMID 28785378, 2017). "In this review, three of the most characterized plasminogen receptors involved in tumorigenesis, namely Annexin 2 (ANX2), Cytokeratin 8 (CK8) and alpha-Enolase (ENOA), are analyzed to ascertain an overall view of their role in the most common cancers." (PMID 23594883, 2013). "The stem cell cluster was identified as the cancer stem cells (CSCs) by upregulating the CSCs markers, such as CD55, ERBB3, KRT8, in the volcano plot based on the differentially expressed genes (DEGs, following the STOmicsDB platform default standards) of the stem cell." (PMID 40822927, 2025). "Several substrates of PTP4A3 have been reported, including FZR1, Keratin 8, Integrin β1, and Leo l, where the phosphorylation levels of the substrates are regulated by PTP4A3, thereby affecting cancer-related signaling pathways and cancer progression." (PMID 38611852, 2024). "The spatial domain 2 were enriched in the GO terms and KEGG pathways of cell differentiation, and included cell markers, such as EPCAM, KRT8, and CLDN3, which are connected with epithelial carcinogenesis, epithelial-mesenchymal transition (EMT) or cancer enhancement." (PMID 38972896, 2024). "Among the identified eProts keratin 8 (cytosqueletton), nucleoline (nucleus), ER-receptor (nucleus), or GRP78 (cytoplasmic) were all found either at the plasma membrane or in the extracellular domain under various pathological conditions such as cancer." (PMID 38606907, 2024). "Notably, the cancer-related genes CA9 and NDUFA4L2 and the epithelial marker genes KRT8 and EPCAM were expressed across cell states 1, 2, 3, and 5, and before the second differentiation node, marking the presence of TECs." (PMID 39301023, 2024). "Therefore, keratins are used as commercially available markers to diagnose cancer: TPS (KRT18), TPACYK (KRT8/18) and CYFRA 21-1 (KRT19)." (PMID 36949761, 2023). "MF HSC/MPP showed a high expression of immune and inflammatory pathways (HLA genes, GBP4, and IFITM1), a matrix- and collagen-degrading enzyme (MMP2), and genes with oncogenic function (MYCN, KRT8, and KRT18) that have been correlated with cancer progression and poor survival." (PMID 34525349, 2021).
cancer (continued). "Interestingly, 5 out of the top 10 hub genes in the network are cancer genes, including ELF3, SLC10A4, ANXA9, DEFB118, KRT8." (PMID 32064261, 2020). "Overall, the adverse contribution of KRT8 in cancer is not novel and it seems to find a possible explanation in the phosphorylation of the protein." (PMID 31781306, 2019). "Since these two cell lines externalized KRT8 and KRT19, and the fetal calf serum in which they were cultured contained CXCL12, we determined whether the CXCL12–KRT19 coating could be formed in vitro by these cancer cells." (PMID 35046049, 2022). "Interestingly, KRT13+ cancers cells consistently display a luminal profile, with absent P63 expression and strong KRT8 and PSA." (PMID 27711225, 2016). "ASCL1 KO tumors developed a poorly differentiated carcinoma without detectable expression of the NE lineage markers SYP, INSM1, or DLL3 but showed higher expression of NOTCH2, HES1, and KRT8." (PMID 39024561, 2024).
adenocarcinoma (34 papers, 2009 to 2025). A common cancer characterized by the presence of malignant glandular cells. "On the other hand, adenocarcinoma had higher luminal keratin and AR expression with low expression of NE-associated genes (represented as Krt8-high:Syp-low: AR-high)." (PMID 38168280, 2023). "While some regions reacquired PRAD histological features (moderate-to-well-differentiated adenocarcinoma harboring KRT8 and AR expression), the predominant histology was high-grade ASCL1− NEPC with sarcomatoid-like features." (PMID 39394434, 2024). "Single cell gene analysis showed that some SCCs positive for KRT14 expressed the adenocarcinoma marker KRT8 as well as the EMT markers VIM, and ZEB2." (PMID 29079795, 2017). "Moreover, LCM-derived RNA-seq analysis confirmed that these KRT-8-high, SYP-low adenocarcinoma cells expressed gene signatures associated with epithelial differentiation and were depleted of neural lineage–related gene expression." (PMID 37546702, 2023). "Then, by staining for squamous epithelium markers (including KRT5, KRT6A, SFN, and KRT14) and columnar epithelium markers (including EPCAM and KRT8), groups 3, 7, and 10 were identified as squamous cancer cells, and groups 5, 6, and 8 were identified as adenocarcinoma cells." (PMID 36052088, 2022). "Interestingly, the increased expression of KRT8/18 in adenocarcinoma is related with a better prognosis." (PMID 33441834, 2021). "For example, keratins KRT8, KRT18, and KRT19 are expressed in most adenocarcinomas." (PMID 35267493, 2022).
infection (9 papers, 2008 to 2025). The state of being infected such as from the introduction of a foreign agent such as serum, vaccine, antigenic substance or organism. "We observed 50% survival by post-infection day 14, a modest recruitment of neutrophils, and the presence of patchy Krt5 and Krt8 staining in lungs that also contained regions of normal alveolar structure." (PMID 40494897, 2025). "Their lungs contained numerous neutrophils on post-infection day 3 and extensively injured Krt5+ and Krt8+ fibrotic alveoli." (PMID 40494897, 2025). "Interestingly, the Krt8 gene is significantly down-regulated at the site of infection in our model at Day 4 (LFC -1.31)." (PMID 25901897, 2015). "We therefore tested the same samples for keratin 8 cleavage to rule out major differences between our infection conditions and the published ones." (PMID 18769617, 2008). "The observed discrepancy could not be attributed to the infection conditions as we have detected a decrease in protein levels of keratin 8, a substrate of chlamydial protease-like activity factor, CPAF, with the onset of chlamydial growth, in our experiments." (PMID 18769617, 2008).
cardiovascular disease (1 paper, 2019). "However, in the context of other reports cited above combined with our results, it is likely that Keratin 8 is involved as a self-antigen in cardiovascular disease." (PMID 30811493, 2019).
kidney diseases (1 paper, 2025). "In several studies, decreased Krt8 expression in kidney diseases has been associated with tubular cell loss." (PMID 40538499, 2025).
KRT8 also shares sentences with these, for which no sentence is quoted: sarcomatoid carcinoma (6 papers); sarcoma (5); cholangiocarcinoma (4); Barrett’s oesophagus (3); endometrial cancer (3); idiopathic pulmonary fibrosis (3); paraganglioma (3); Prostatic adenocarcinoma (3); prostatic intraepithelial neoplasia (3); adenosquamous carcinoma (2); angiosarcoma (2); bladder cancer (2); colon adenocarcinoma (2); dysplasia (2); esophageal cancer (2); head and neck squamous cell carcinoma (2); hepatocellular adenoma (2); invasive carcinoma (2); leukoplakia (2); lung squamous cell carcinoma (2); mesothelioma (2); metastatic tumor (2); mucoepidermoid carcinoma (2); nasopharyngeal carcinoma (2); Obesity (2); pancreatic adenocarcinoma (2); serous ovarian carcinoma (2); small cell lung carcinoma (2); steatosis (2); acinic cell carcinoma (1).
A further 86 diseases each share a sentence with KRT8 in 1 paper.